TFF3 (trefoil factor 3)
Diseases named in the same sentence as TFF3 in open-access papers (continued):
Sharing a sentence is not in itself a finding about the gene and the disease.
diabetes (9 papers, 2019 to 2025). "Existing studies have primarily concentrated on assessing TFF3 changes in diabetic patients or examining the potential of TFF3 as a diagnostic biomarker for diabetes." (PMID 38710764, 2024). "Complete loss of Tff3 expression was the most prominent expressional change during the early stages of diabetes in the liver of the polygenic mice model of diabesity, and since then its role in relevant metabolic processes has emerged." (PMID 31500117, 2019). "It has been found that Tff3 liver expression is reduced in various mouse models of obesity and diabetes (genetic and dietary) compared to healthy controls." (PMID 40426854, 2025). "The first link between Tff3 and metabolism emerged from a study using a polygenic mouse model of diabetes and obesity (TallyHo)." (PMID 40426854, 2025). "The downregulation of Tff3 expression has also been found in other genetic mouse models of obesity and diabetes (ob/ob, db/db) as well as in models of hepatic steatosis and mouse models of diet-induced obesity." (PMID 40426854, 2025). "This suggests that the TFF3 gene knockout reduces the chronic inflammatory response incited by diabetes." (PMID 38710764, 2024). "This study aims to evaluate the role of trefoil factor 3 (TFF3) peptides in type 2 diabetes mellitus (T2DM) from an inflammatory perspective." (PMID 38710764, 2024). "Elevated urinary TFF3 levels have been found in people of African descent, patients with diabetes and those taking blood pressure-lowering drugs." (PMID 37569301, 2023). "The only study conducted on patients in the context of diabetes research showed that type 1 diabetes (T1D) patients have decreased serum TFF3 levels compared to healthy controls, which increased after insulin treatment." (PMID 36013467, 2022). "Microarray analysis showed that TFF3 was one of the most affected liver genes in rodent models of early fatty liver and diabetes." (PMID 35039476, 2022). "Downregulation of Tff3 gene expression in the liver has also been reported in several genetic, as well as diet-induced, mouse models of obesity and diabetes, as well as hepatic steatosis." (PMID 36013467, 2022). "Complete ablation of Tff3 expression is observed in steatosis, and as the most prominent change in the early phase of diabetes in multigenic mouse models of diabesity." (PMID 31500117, 2019). "Serum TFF3 levels are downregulated in serum of diabetes mellitus type 1 patients, and the presence of glucose and insulin results in elevated serum levels of TFF3." (PMID 31817054, 2019). "Therefore, our study intend to investigate the role of TFF3 in high glucose-cultured T lymphocytes, as well as in a mouse model of type 2 diabetes mellitus (T2DM)." (PMID 38710764, 2024). "Precisely, mouse models of obesity and diabetes (ob/ob, db/db, DIO-C57BL6J) display a fatty liver phenotype characterised by the increased accumulation of lipid droplets and hepatocyte damage, and the downregulation of Tff3 expression in the liver is observed in these models." (PMID 40426854, 2025). "Tff3 was found to be transcriptionally active in the liver tissue of healthy C57BL/6 control mice, but was almost absent in the TallyHo diabetes/obesity model." (PMID 40426854, 2025). "Other studies investigated the role of u-TFF3 in patients with CKD with and without diabetes." (PMID 38093293, 2023).
ulcerative colitis (9 papers, 2013 to 2024). An inflammatory bowel disease involving the mucosal surface of the large intestine and rectum. "Consistent with our findings, it has been shown that Astragalus polysaccharide (AP) and Matrine ameliorate histopathological changes in rats with ulcerative colitis, with increased expression of ZO-1, occludin, and TFF3 in lung and colon tissues." (PMID 39588099, 2024). "Currently, only recombination TFF3 has entered clinical practice; it is used for treating ulcerative colitis and oral mucositis and produced by recombinant expression in yeast." (PMID 35039476, 2022). "No positive effects of TFF3 were observed in a phase I/II double-blind randomized trial of TFF3 enema combined with oral 5-aminosalicylic acid in the treatment of ulcerative colitis." (PMID 35039476, 2022). "Studies have showed that TFF3 was a regulator of many gastrointestinal diseases such Ulcerative colitis and Crohn’s disease." (PMID 34347831, 2021). "TFF-3 levels correlate with the activity of ulcerative colitis localized to the colonic mucosa, suggesting the site-specific upregulation of TFF-3 in inflamed colonic mucosa." (PMID 32190704, 2020). "In one of our another study, we observed a higher level of serum trefoil factor-3 in the serum of patients with healed stage of ulcerative colitis in comparision to those having active disease." (PMID 26988818, 2016). "Given its prominent role in cell migration, TFF3 was investigated as a potential wound healing factor to repair the gut epithelium damage observed during the progression of ulcerative colitis." (PMID 26083576, 2015). "The aim of the study was to analyze expression of mucins (MUC2, MUC3, and MUC4) and trefoil factor-3 (TFF3) and its influence on colon mucosal barrier in patients with ulcerative colitis and Crohn's disease." (PMID 23737764, 2013). "Recombinant TFF3 protein has been delivered in humans via enema in combination with oral 5-aminosalicylic acid (5-ASA) for the treatment of mild-to-moderate left-sided ulcerative colitis." (PMID 26083576, 2015).
breast tumors (8 papers, 2004 to 2023). "The expression of TFF3 mRNA was associated with oestrogen receptor mRNA in breast tumours (Pearson's coefficient=0.762, P=0.000)." (PMID 25900183, 2015). "The expression of TFF3 was measured next by northern transfer and RT-PCR analysis in a panel of breast tumours." (PMID 25900183, 2015). "The positive association between oestrogen receptor and TFF3 expression indicates that TFF3 expression is oestrogen dependent in a majority of breast tumours." (PMID 25900183, 2015). "TFF3 protein was expressed in the majority of the breast tumours analysed." (PMID 25900183, 2015). "There was a good correlation between breast tumour TFF3 mRNA and protein expression." (PMID 25900183, 2015). "In breast tumor tissue, TFF1 and TFF3 expression levels were inversely related to proliferation index (Ki67) and tumor grade." (PMID 36818673, 2022).
dementia (8 papers, 2018 to 2024). Loss of intellectual abilities interfering with an individual's social and occupational functions. "TFF3 has been detected in several regions of the brain, where it acts as neuropeptide participating in several processes such as inflammation, memory and dementia development." (PMID 39519214, 2024). "Heterogeneity in the magnitude of the protein-dementia associations was observed among APOEε4 carriers for one NCR1 (one of the top four candidate proteins), GDF15, CHI3L1, and TFF3, each of which showed significant associations with VaD and comparatively weaker associations with AD dementia." (PMID 39482741, 2024). "Clinical findings have shown that TFF3 is the strongest predictor of neurodegeneration across the spectrum of cerebral amyloidosis, with significant reductions in TFF3 levels observed in patients with vascular parkinsonism dementia, Parkinson’s disease dementia, and Alzheimer’s disease." (PMID 35039476, 2022). "Since several lines of evidence show that TFF3, ChE and Hcy may be involved in the pathogenesis of dementia, we specifically explored the relationships among serum TFF3, ChE and Hcy." (PMID 29392081, 2018). "Although both TFF3 and Hcy are correlated with endothelial cell efficiency and declining cognition, the association of TFF3/Hcy levels with the severity of dementia in PD and VP has not been systemically evaluated." (PMID 29392081, 2018). "Trefoil factor 3 (TFF3), cholinesterase activity (ChE activity) and homocysteine (Hcy) play critical roles in modulating recognition, learning and memory in neurodegenerative diseases, such as Parkinson’s disease dementia (PDD) and vascular parkinsonism with dementia (VPD)." (PMID 29392081, 2018). "Decreased serum trefoil factor 3 (TFF3)/cholinesterase (ChE) activity and increased homocysteine (Hcy) are associated with vascular function, inflammation, and oxidative stress, which may underlie the pathophysiological mechanisms of PD dementia (PDD) and vascular parkinsonism with dementia (VPD)." (PMID 33328961, 2020). "Compared with healthy subjects, the serum levels of Trefoil factor 3 (TFF3) and cholinesterase activity were lower, while homocysteine (Hcy) was higher in patients with Parkinson's disease dementia (PDD) and vascular parkinsonism with dementia (VPD)." (PMID 33568988, 2020).
endometrial cancer (8 papers, 2008 to 2026). Primary or metastatic malignant neoplasm involving the endometrium (mucous membrane that lines the endometrial cavity). "Increased expression of TFF3 has been observed in some cancers, including breast, lung, liver, prostate, gastric, and endometrial cancers." (PMID 37569301, 2023). "Other estrogen-responsive genes upregulated in CTCF-altered cancers, namely SPDEF, TFF3 and PIGR, are also components of these gene signatures, indicating that loss of CTCF could be an important factor determining endometrial cancer progression and pathology." (PMID 30513694, 2018). "This study aimed to evaluate trefoil factor 3 (TFF3), secreted frizzled-related protein 4 (sFRP4), reactive oxygen species modulator 1 (Romo1) and nuclear factor kappa B (NF-κB) as diagnostic and prognostic markers of endometrial cancer (EC) and ovarian cancer (OC)." (PMID 35461390, 2022). "Furthermore, the expression of estrogen-responsive genes KIAA1324, MLPH, MSX2, SPDEF, TFF3, and PIGR were all significantly up-regulated in CTCF-altered endometrial cancers (p = 0.0004, 0.0007, 0.0032, 0.0009, 0.0122, and 0.0028 respectively)." (PMID 30513694, 2018). "In contrast, a recent histopathological study in type 1 endometrial carcinoma observed that tumour expression of TFF3 predicted lack of lymphovascular invasion, a lower recurrence and higher survival of patients." (PMID 25266665, 2014). "Finally, when we analysed the combined ability of CA125 and TFF3 serum markers in detecting endometrial cancer, we found no significant improvement when compared with TFF3 alone." (PMID 18682706, 2008).
chronic kidney disease (7 papers, 2013 to 2023). Impairment of the renal function secondary to chronic kidney damage persisting for three or more months. "Circulating TFF3 levels are dramatically elevated in chronic kidney disease, which in turn is correlated with an elevated risk to develop cancers." (PMID 26083576, 2015). "In this large-sample investigation chronic kidney disease (CKD) was associated with increased serum TFF3 concentrations." (PMID 24282531, 2013). "The results show that serum levels of TFF3 are significantly higher in patients with chronic kidney disease (CKD) than in controls." (PMID 37569301, 2023). "TFF3 levels also increased in the urine of patients with worsening chronic kidney disease, and in combination with the presence of microalbuminuria, this protein may be a predictor of a worse prognosis." (PMID 37569301, 2023). "Furthermore, a higher serum level of TFF3 was detected in patients with chronic kidney disease, metastatic and secondary carcinoma, and acute gastroenteritis." (PMID 31817054, 2019). "Elevated levels of TFF3 were also found in urine from patients with incident chronic kidney disease as part of a nested case-control study, as well as in serum of patients with CKD stages 1–5." (PMID 29850501, 2018).
dysplasia (7 papers, 2015 to 2026). A usually neoplastic transformation of the cell, associated with altered architectural tissue patterns. "MUC2 was reduced in 8.2% (5/61) of LGD or lost in 11.1% (4/33) of EAC, while TFF3 was positive in all GCs of BE and BE-associated dysplasia." (PMID 39001449, 2024). "We also found that the expression level of TFF3 gradually decreased during the BE metaplasia-to-dysplasia to EAC progression and during the GIM to GA progression." (PMID 36994101, 2023). "Notably, cytosponge-TFF3 testing could offer a feasible, safe, and acceptable screening method for the early diagnosis of treatable dysplasia and early cancer through a patient-swallowed sponge that collects esophageal epithelial cells for analysis." (PMID 41439274, 2026). "Specifically, during normal esophageal squamous, BE metaplasia, dysplasia, and EAC progression there is a progressive increase in TFF2, TFF3, MUC2, MUC5AC, MUC6, CDX2 with the development of intestinal metaplasia." (PMID 36994101, 2023). "The sensitivity for diagnosing BE increased with the circumferential length of the BE segment up to 87.2% (95% CI 83.0%–90.6%, Cochran-Armitage trend test, p < 0.001), and TFF3 positivity was not reduced in the presence of dysplasia (Cochran-Armitage trend test, p = 0.253)." (PMID 25634542, 2015).
Obesity (7 papers, 2005 to 2025). Accumulation of substantial excess body fat. "TFF3 overexpression mediated by an adeno-associated virus (AAV) vector in a diet-induced obesity of B6D2F1/J mice (BDF-DIO) improved glucose tolerance, without affecting body weight, fasting plasma insulin, triglyceride, cholesterol or leptin levels." (PMID 26083576, 2015). "To further elucidate the role of the Tff3 protein in obesity-related diseases, we have developed a new congenic Tff3-deficient mouse strain on the C57Bl&N (Tff3−/−/C57Bl6N) genetic background that has no additional mutations that could affect metabolic pathways." (PMID 40426854, 2025). "In numerous mouse models of obesity, Tff3 has been found to be downregulated in the liver and its overexpression is associated with an improvement in metabolic parameters." (PMID 40426854, 2025). "Regulation of Tff3 with appropriate food intake and improvement in glucose tolerance in a diet-induced obesity model raises additional questions regarding the involvement of Tff3 in metabolic pathways." (PMID 38003531, 2023). "We found that increased levels of TFF3 improved glucose tolerance in a diet-induced obesity mouse model." (PMID 26083576, 2015). "TFF3, which maps to the Obq4 obesity quantitative trait locus (QTL), was the most significantly changed of all genes analyzed." (PMID 26083576, 2015). "Overexpression of TFF3 using a recombinant adeno-associated virus (AAV) vector, or daily administration of recombinant TFF3 protein in vivo improved glucose tolerance in a diet-induced obesity mouse model." (PMID 26083576, 2015). "Trefoil 3 (Tff3), which maps to the Obq4 obesity QTL, was the most significantly changed of all genes analyzed." (PMID 15760467, 2005). "Additionally, Tff3 improved the glucose tolerance in a diet-induced obesity model, raising the question of the involvement of Tff3 in metabolic pathways." (PMID 38003531, 2023). "TFF3 also localizes on the Obq4 obesity QTL locus resulting from an AKR/J and C57L/J intercross." (PMID 26083576, 2015). "On the other hand, TFF3 improves HFD-induced hepatic steatosis and, in a diet-induced obesity mouse model, TFF3 improved glucose tolerance." (PMID 34944474, 2021). "Although TFF2 has a different distribution along the GI tract than TFF3, genetic ablation of TFF2 confers resistance to diet-induced obesity corroborating the role of TFF family peptides interact in metabolic regulation." (PMID 26083576, 2015). "In contrast, overexpression of Tff3 improved glucose tolerance in B6D2F1 mice fed an HFD for 6 weeks, in male Lepr db/Leprdb (db/db) mice and Leprob/Leprob (ob/ob) and in the diet-induced obesity mouse model (8-week-old C57BL/6 mice fed an HFD for more than 8 weeks)." (PMID 36013467, 2022).
kidney damage (6 papers, 2013 to 2025). "Our study further explored the potential biomarkers of kidney damage in plasma and showed significant differences in the levels of cystatin C, TFF3, and uromodulin between patients with progressive nephropathy and their control subjects." (PMID 39937009, 2025). "As concerns urinary biomarkers of kidney damage, u-TFF3 was higher in NA-DKD patients versus controls (1533.14 ± 878.31 ng/mL vs. 1253.84 ± 682.17 ng/mL, P = 0.047)." (PMID 38093293, 2023). "Based on its biological effects, TFF3 may play key roles in regeneration and restitution processes and in the ongoing repair of kidney damage." (PMID 24282531, 2013). "FDA-approved representative biomarkers N-acetyl-beta-D-glycosaminidases (NAG), inflammatory mediators (trefoil factor-3 (TFF3), inflammatory mediators (trefoil factor-3 (TFF3)), glomerular filtration markers (Cyst C) and β2-microglobulin (β2-Mic) are used to diagnose kidney damage." (PMID 36273205, 2022).
thyroid tumor (6 papers, 2004 to 2022). A benign or malignant neoplasm affecting the thyroid gland. "We also integrated differentially downregulated DEGs from the datasets and identified six downregulated DEGs, namely, MPPED2, TNFRSF11B, FHL1, CRABP1, MATN2, and TFF3, collectively known as thyroid tumor-downregulated genes (TTDGs)." (PMID 35990603, 2022). "By contrast, in most thyroid tumors and in retinoblastoma TFF3 expression is decreased." (PMID 31450568, 2019). "By contrast, a recent study demonstrated that TFF3 is downregulated in most thyroid tumors." (PMID 27626280, 2016). "On a single gene basis, FNAB of histologically proven malignant thyroid tumours (n=18) showed significantly lower mRNA expression levels for TFF3 and HGD1 and significantly higher mRNA levels for ADM3 and LGALS3 compared with FNAB of benign thyroid tumours (n=93)." (PMID 22223087, 2012). "Messenger RNA expression for individual marker genes was demonstrated in 109 (TFF3), 99 (LGALS3), 95 (ADM3), 84 (HGD1) and 67 (PLAB) of 111 fine-needle biopsies obtained from the thyroid tumours and in all 45 samples obtained from normal thyroid tissues." (PMID 22223087, 2012). "As TFF3 mRNA is abundantly expressed in thyroid tumours, measurement of the copy number in FNAB samples may not be difficult." (PMID 15083192, 2004).
acute kidney injury (5 papers, 2015 to 2023). Sudden and sustained deterioration of the kidney function characterized by decreased glomerular filtration rate, increased serum creatinine or oliguria. "In studies regarding drug-induced acute kidney injury, urinary TFF3 level has shown discrepant results." (PMID 34768522, 2021). "In acute kidney injury (AKI) of animal models, a decrease in both urine TFF3 levels and renal TFF3 staining was observed in nephrotoxin-treated rodents, suggesting a gene regulatory response of TFF3 to tubular toxicity in this setting." (PMID 29850501, 2018).